HMOX1 (heme oxygenase 1)
Diseases named in the same sentence as HMOX1 in open-access papers (continued):
Sharing a sentence is not in itself a finding about the gene and the disease.
nasopharyngeal carcinoma (10 papers, 2008 to 2025). A carcinoma arising from the nasopharyngeal epithelium. "Picrasidine I was also found to induce apoptosis in nasopharyngeal carcinoma by modulating heme oxygenase 1 via AKT and ERK signaling pathways." (PMID 37686036, 2023). "It was also shown that cephalosporin antibiotics induced Hmox1 specifically and selectively, which finally activated ferroptosis and inhibited the proliferation of nasopharyngeal carcinoma." (PMID 37424906, 2023). "In addition, a similar result was found in GSE12452 from the GEO database, in that the mRNA level of HMOX1 was lower in nasopharyngeal carcinoma tissues than normal nasopharyngeal tissues." (PMID 35682782, 2022).
nonalcoholic steatohepatitis (10 papers, 2010 to 2024). "Heme oxygenase 1 (HO-1) has an influential but insufficiently investigated effect on ferroptosis, which is a novel form of programmed cell death and may play an effect on nonalcoholic steatohepatitis (NASH)." (PMID 37422643, 2023). "HMOX1 expression is increased in non-alcoholic steatohepatitis (NASH) patients and an in vitro study suggests that HMOX1 may have a protective role by suppressing endoplasmic reticulum stress in hepatocytes." (PMID 39135705, 2024).
renal cell carcinoma (10 papers, 2012 to 2024). "Luteolin demonstrates an anticancer effect on clear renal cell carcinoma by upregulating heme oxygenase-1 (HO-1) expression and activating labile iron pool (LIP)directly, thus triggering ferroptosis." (PMID 38738174, 2024). "Hyperactivation of the receptor tyrosine kinase c-Met and overexpression of the cytoprotective enzyme heme oxygenase-1 (HO-1) play a critical role in the growth and progression of renal cell carcinoma (RCC)." (PMID 28724911, 2017). "Nevertheless, NRF2 was also reported to trigger ferroptosis via increasing the expression of HMOX1 in lung cancer and renal cell carcinoma (RCC) cells." (PMID 37488128, 2023).
retinal ischemia (10 papers, 2014 to 2025). A ischemic disease that involves the retina. "Heme oxygenase-1 (HO-1) is involved in the cellular response to oxidative stress and hypoxia, and elevated levels of HO-1 can protect against retinal ischemia and/or AMD via its antioxidative activity." (PMID 27617027, 2016). "For instance, in models of retinal ischemia/reperfusion injury, RSV modulates the expression of matrix metalloproteinase-9 (MMP-9), inducible nitric oxide synthase (iNOS), and heme oxygenase-1 (HO-1), contributing to reduced vascular leakage and cell death." (PMID 40807437, 2025).
aneurysm (9 papers, 2010 to 2026). Bulging or ballooning in an area of an artery secondary to arterial wall weakening. "First, mRNA expression levels of TGF-β1 and heme oxygenase 1 were not consistent with prior reports of compensatory upregulation in response to aneurysm formation, although their specific roles in AAA pathogenesis remain controversial." (PMID 23226500, 2012).
asplenia (9 papers, 2014 to 2021). "This included genes associated with asplenia i.e. GJA1, HMOX1, RPSA, STIM1 and AIRE." (PMID 34781974, 2021). "Nine cases of human mutations in HMOX-1 encoding for HO-1 were reported in the literature and the majority of these patients were characterized with chronic inflammation, hemolysis and asplenia, thus further corroborating the critical roles of HO-1 for maintaining blood homeostasis." (PMID 34573346, 2021). "GJA1, HMOX1 and RPSA, have been described as defective in isolated congenital asplenia." (PMID 34781974, 2021).
cholestasis (9 papers, 2015 to 2024). Impairment of the bile flow caused by obstruction within the liver, or outside the liver in the bile duct system. "Here, we investigated the effects of HMOX1 induction by heme on ethinylestradiol-induced cholestasis and possible underlying mechanisms." (PMID 25683492, 2015). "We conclude that HMOX1 induction by heme increases hepatocyte transporter expression, subsequently stimulating bile flow in cholestasis." (PMID 25683492, 2015). "In this study, we demonstrated that the induction of HMOX1 with its substrate, heme, can confer protection against EE-induced cholestasis by increasing both liver and renal clearance of BA in a rat model." (PMID 25683492, 2015). "Thus, the HMOX1 induction might represent a potential therapeutic strategy for the treatment of estrogen-induced cholestasis." (PMID 25683492, 2015). "Thus, HMOX1 induction may be a potential therapeutic strategy for the treatment of ethinylestradiol-induced cholestasis." (PMID 25683492, 2015). "However, to our knowledge, HMOX1 knockout rats are not available and mice do not develop cholestasis after EE administration and thus cannot be used for this type of experiments." (PMID 25683492, 2015).
chronic heart failure (9 papers, 2013 to 2025). "Intramyocardial injection of AAV serotype 2 vectors encoding human heme oxygenase-1 has also been investigated in a rat model of cardiac remodeling and development of chronic heart failure." (PMID 34829874, 2021). "Moreover, long-term induction of heme oxygenase-1 by chronic hemin administration exerted protective effects in a rat model of chronic heart failure induced by permanent ligation of the left anterior descending coronary artery." (PMID 34829874, 2021). "Additionally, it has been reported previously that the H2S donor, NaHS, reduced chronic heart failure, possibly due to upregulation of HMOX-1 mRNA expression." (PMID 34069086, 2021).
endometritis (9 papers, 2020 to 2026). An acute or chronic, usually bacterial infectious process affecting the endometrium. "Furthermore, elaborated that there was considerable up-regulation of the expression level of HMOX1 in endometritis ewes." (PMID 40872670, 2025). "Our findings showed that the buffaloes with endometritis had significantly higher TLR4, IL-8, IL-17, NFKB, SLCA11A1, NCF4, Keap1, HMOX1, OXSR1, ST1P1, and SERP1 expression levels." (PMID 39195794, 2024). "The buffaloes with endometritis had considerably higher expression levels of TLR4, IL-8, IL-17, NFKB, SLCA11A1, NCF4, Keap1, HMOX1, OXSR1, ST1P1, and SERP1." (PMID 39195794, 2024). "TLR4, IL-8, IL-17, NFKB, SLCA11A1, NCF4, Keap1, HMOX1, OXSR1, ST1P1, and SERP1 were manifestly expressed at much higher levels in the buffaloes with endometritis." (PMID 39195794, 2024). "The following genes were assessed for their expression levels using real-time PCR in both the normal and endometritis-affected buffaloes: immune (TLR4, IL-8, IL-17, NFKB, SLCA11A1, and NCF4) and antioxidant (SOD, CAT, NDUFS6, Nrf2, Keap1, PRDX2, HMOX1, OXSR1, ST1P1, and SERP1)." (PMID 39195794, 2024).
Infertility (9 papers, 2014 to 2023). "Surviving Hmox1–/– female mice were initially wrongly reported as infertile." (PMID 25628565, 2014).
sarcoma (9 papers, 2004 to 2025). A usually aggressive malignant neoplasm of the soft tissue or bone. "ALA administration increased heme oxygenase 1 (HO-1) expression in both cell types; when carbon monoxide (CO), a metabolite of HO-1, was administered to sarcoma cells via carbon-monoxide-releasing molecule 2 (CORM2), it enhanced sphere-forming ability." (PMID 37047157, 2023). "The ferroptosis inducer erastin was shown to induce expression of the NRF2 target gene HMOX-1 in HT-1080 sarcoma cells; inhibition of HMOX-1 with 10 μM zinc protoporphyrin eliminated sensitivity to erastin-induced ferroptosis." (PMID 28793787, 2018).
tauopathy (9 papers, 2016 to 2025). Neurodegenerative disorders involving deposition of abnormal tau protein isoforms (tau proteins) in neurons and glial cells in the brain. "Indeed, the neurons of tauopathy patients and animal models display elevated OS For example, the Pick bodies of PiD patients and the threads and glial inclusions of CBD patients exhibited increased levels of the oxidative marker heme oxygenase-1 (HO-1)." (PMID 35892623, 2022).
bacterial sepsis (8 papers, 2013 to 2025). "The results showed that compared to the bacterial sepsis group, the expression of ferroptosis hub genes IL1-β and HMOX1 was decreased in the coronavirus-associated viral sepsis group." (PMID 40370730, 2025). "In bacterial Sepsis-Associated ALI, endotoxins have been shown to suppress the NRF2/heme oxygenase-1 (HO-1) signaling pathway, exacerbating AEC inflammation, oxidative stress, and ferroptosis." (PMID 40842982, 2025).
brain hemorrhage (8 papers, 2019 to 2025). "After brain hemorrhage, heme processing enzymes are upregulated in microglia, including heme oxygenase-1 (HO-1), which is an inducible rate-limiting enzyme that converts heme/hemin to carbon monoxide, biliverdin, and ferrous iron." (PMID 35805174, 2022). "HMOX1 was also upregulated when pericytes were exposed to iron and is known to be enriched in microglia and the perivascular spaces promoting secondary brain injury after intracranial hemorrhage." (PMID 40001467, 2025). "Together with HMOX-1’s role in catalyzing heme degradation, these findings may suggest HMOX-1 has a specific function to attenuate heme-related damage after brain hemorrhage and protect against subsequent cellular heme/iron overload." (PMID 38283681, 2023).
breast tumor (8 papers, 2018 to 2025). "According to our previous study, phagocytic engulfment of breast tumor cell debris by TAMs attenuated chemotherapeutic efficacy through the upregulation of heme oxygenase-1 (HO-1)." (PMID 33809707, 2021). "In addition, HMOX1 mRNA abundances in primary breast tumors of all 4 molecular subtypes were higher than in normal breast tissues." (PMID 37217939, 2023).
dermatitis (8 papers, 2018 to 2024). An inflammatory process affecting the skin. "Given the importance of oxidative stress in stimulating skin inflammation, the nuclear factor erythroid 2-related factor 2 (Nrf2)/heme oxygenase-1 (HO-1) signaling pathway has gained increasing attention." (PMID 39684446, 2024).
esophageal squamous cell carcinoma (8 papers, 2019 to 2025). Esophageal squamous cell carcinoma (ESCC) is a type of esophageal carcinoma (EC) that can affect any part of the esophagus, but is usually located in the upper or middle third. "Recent studies have shown that high GPX4 expression levels and low HMOX1 expression levels are poor prognostic factors for patients with esophageal squamous cell carcinoma." (PMID 35562364, 2022). "For example, 5-ALA induces ferroptosis via regulation of GPX4 and heme oxygenase 1 (HMOX1) and exerts antitumor effects in esophageal squamous cell carcinoma cell lines and BALB/cAJcl-nu/nu mice with subcutaneously transplanted KYSE30 cells." (PMID 35562364, 2022).
gastritis (8 papers, 2015 to 2025). Inflammation of the stomach. "In summary, the prevention and therapy of VE have significant protective effects on stress‐induced gastritis via promoting Nrf2/Hmox1/NQO1 and inhibiting NF‐κB signalling pathways." (PMID 40418631, 2025). "VE displayed significant antioxidant properties in stress‐induced gastritis via activating the Nrf2/Hmox1/NQO1 pathway." (PMID 40418631, 2025). "Consequently, it can be considered that the Nrf2/Hmox1/NQO1 pathway is most likely responsible for mediating the oxidative stress‐resistant properties of VE in stress‐induced gastritis." (PMID 40418631, 2025). "Resv also significantly suppresses the levels of IL-8 (interleukin 8) and iNOS (Inducible nitric oxide synthase) and improves the antioxidant status by upregulating the Nrf2/HO-1 (Nuclear factor-E2-related factor/Heme oxygenase-1) signaling pathway in the H. pylori-induced gastritis model." (PMID 33917379, 2021).
gastroparesis (8 papers, 2017 to 2025). Paralysis of the muscles of the stomach wall resulting in delayed emptying of the gastric contents into the small intestine. "Possible associations were investigated between polyGT allele length in HMOX1 genes and type of diabetes, levels of HbA1c and specific symptoms of gastroparesis defined by the gastroparesis cardinal symptom index (GCSI)." (PMID 29161307, 2017). "Our data do not support a strong link between the poly GT repeat allele in HMOX1 and idiopathic gastroparesis despite the similarities in the pathological changes observed in diabetic and idiopathic gastroparesis of humans." (PMID 29161307, 2017). "In a gastroparesis animal model, one study demonstrated that oxidative stress and damage of the pacemaker cells or enteric nerves was caused by depletion of resident M2 anti-inflammatory macrophages that express heme oxygenase-1 (HO-1)." (PMID 35145413, 2022). "The decrease in HMOX1 which encodes heme-oxidase 1 an enzyme expressed in M2 macrophages that helps protect against oxidative stress would be consistent with previous studies suggesting an increase in the M1/M2 macrophage ratio in gastroparesis." (PMID 31221130, 2019). "For this study, we investigated heme oxygenase 1 (HO1) as a possible susceptibility factor for gastroparesis due to evidence from animal models of diabetic gastroparesis showing that elevated HO1 expression protects diabetic mice from development of delayed gastric emptying." (PMID 29161307, 2017). "We also set out to examine whether any specific symptoms of gastroparesis are associated with the longer polyGT repeat allele in the promoter of the HMOX1 gene." (PMID 29161307, 2017). "Downregulation of HMOX1 gene expression plays a causal role in diabetic gastroparesis in animal models, and additional studies have demonstrated that polyGT alleles of HMOX1 were longer in patients with gastroparesis, which was most pronounced in patients with type 2 diabetic gastroparesis." (PMID 40218285, 2025). "Longer poly-GT repeats in the HMOX1 gene are more common in African Americans with gastroparesis." (PMID 29161307, 2017). "Large, fully powered studies that take into account race are necessary to compare the allelic differences in the HMOX1 gene in all of these diseases including gastroparesis, where there is a rationale to consider a role for HO1 in the prevalence and progression of the disease." (PMID 29161307, 2017). "The principal finding of this study is the presence of longer poly GT repeat alleles in the HMOX1 genes of black/African American subjects with gastroparesis compared to the alleles in non-black/African American subjects with gastroparesis." (PMID 29161307, 2017). "It is likely that several hits lead to development of gastroparesis and long poly(GT) repeats in HMOX1 may represent one of these hits especially when the allele length is so long that it leads to very low basal and inducible HO1 protein activity." (PMID 29161307, 2017). "Our hypothesis was that longer polyGT alleles are more common in the HMOX1 genes of individuals with gastroparesis than in controls without upper gastrointestinal motility disorders." (PMID 29161307, 2017). "Therefore the a priori hypothesis of this study was that longer polyGT alleles are more common in the HMOX1 genes of individuals with gastroparesis than in control subjects without upper gastrointestinal motility disorders." (PMID 29161307, 2017). "Several of the predicted PI3K target genes were further examined by qRT-PCR, of these CXCL10 was found to be specifically elevated in high BMI control subjects, whereas HMOX1 and SREBF1 were decreased both in high BMI control subjects and in low BMI subjects with idiopathic gastroparesis." (PMID 31221130, 2019).
glaucoma (8 papers, 2014 to 2024). Increased pressure in the eyeball due to obstruction of the outflow of aqueous humor. "Levels of vitagenes HSP-72, heme oxygenase-1, as well as F2-isoprostanes were significantly higher in the blood of patients with glaucoma than in controls." (PMID 24936186, 2014). "Heme oxygenase-1, another HSP-32 endowed with cytoprotective properties, was found expressed at significantly higher levels in lymphocytes of patients with glaucoma than in controls." (PMID 24936186, 2014).
glomerulonephritis (8 papers, 2010 to 2024). A renal disorder characterized by damage in the glomeruli. "In support of our observation, in a rodent model of thymocyte antigen-1-induced glomerulonephritis, heme oxygenase-1 (HO-1) blockade lowered the expression of FtH and accelerated mesangial cell death." (PMID 33912577, 2021). "Also, heme-oxygenase-1 (HO-1), which can reduce the expression of iNOS, was an effective therapy for glomerulonephritis in MRL/lpr mice." (PMID 32066371, 2020). "Mesangial cells, the extracellular matrix secreting and phagocytic glomerular resident cells, express heme-oxygenase-1 (HO-1) and FtH, and their FtH content was critical in mitigating iron toxicity and mediating the protective effect of HO-1 in response to experimental glomerulonephritis." (PMID 33912577, 2021).
Hypercholesterolemia (8 papers, 2010 to 2024). An increased concentration of cholesterol in the blood. "Western blot analysis further revealed hypercholesterolemia-induced increase and PCE-associated reduction in heme oxygenase-1 expression." (PMID 37686067, 2023).
metastatic disease (8 papers, 2016 to 2024). "HMOX-1 expression was higher in human primary and metastatic tumors, increased levels of HMOX-1 ameliorated oxidative stress, cell death and promoted cell metastasis." (PMID 29416636, 2018).
Miscarriage (8 papers, 2011 to 2025). A pregnancy that ends at a stage in which the fetus is incapable of surviving on its own, defined as the spontaneous loss of a fetus before the 22th week of pregnancy. "During human, rat and mouse pregnancies the expression of heme oxygenase-1 (HO-1) is highly induced at trophoblast level whereas miscarriages and pre-eclampsia were showed to be associated with low HO-1 expression in the placenta." (PMID 22348450, 2012). "The administration of EVs in a heme oxygenase-1 knockout mouse model of PE was able to improve miscarriage rates, fetal growth restrictions, uterine artery remodelling, and maternal PE symptoms." (PMID 40136497, 2025). "In this study, a high dose of LPS was used to clearly establish the effects of the Si-based agent, demonstrating a significant suppressive effect on miscarriage and Hmox1 expression." (PMID 35047922, 2021). "Their research demonstrated that gavaged Quercetin (100 mg/kg) effectively prevents miscarriage by suppressing the expression of pro-inflammatory cytokines, such as IL-6 and Interleukin 8 (IL-8), while upregulating the levels of Heme Oxygenase-1 (HO-1) in peripheral blood." (PMID 40218878, 2025).
schizophrenia (8 papers, 2015 to 2025). A major psychotic disorder characterized by abnormalities in the perception or expression of reality. "Further supporting the link between HO-1 and α-synuclein, HMOX1 overexpression from embryogenesis until 12 months of age, as seen in the GFAP.HMOX10–12 m mouse model of schizophrenia, similarly resulted in significant elevation of α-synuclein mRNA and protein." (PMID 39483365, 2022).
co-infection (7 papers, 2014 to 2022). "Lower expression of HMOX1 in patients with HIV/HCV co-infection can indicate a weaker antioxidative response to oxidative stress in this group of patients." (PMID 24752012, 2014). "Conversely, HMOX1 expression was lowest in patients with HIV/HCV co-infection, especially those with lower CD4 lymphocyte counts and higher HIV viral loads, which is disadvantageous." (PMID 24752012, 2014). "In patients with HIV/HCV co-infection, the expression of HMOX1 was lower in patients with lower lymphocyte CD4 count and higher HIV viral load." (PMID 24752012, 2014). "Reduced expression of HMOX1 in patients with HIV/HCV co-infection may indicate a worse prognosis in this group." (PMID 24752012, 2014).
hemolysis (7 papers, 2014 to 2025). Disruption of the integrity of the erythrocyte membrane causing release of hemoglobin. "Since SCD is associated with elevated heme oxygenase-1 (HO-1) due to chronic hemolysis, SCD may promote tumor growth." (PMID 26161296, 2015). "Moreover, intravascular hemolysis occurs after blood contact with artificial surfaces and is associated with a liberation of hemoglobin, which leads to a reduction in nitrogen oxidation, afferent arterial vasoconstriction, and an increase in heme oxygenase 1 expression." (PMID 39336904, 2024).